LGALS3 (galectin 3)
Diseases named in the same sentence as LGALS3 in open-access papers (continued):
Sharing a sentence is not in itself a finding about the gene and the disease.
gastric cancer (45 papers, 2002 to 2025). A primary or metastatic malignant neoplasm involving the stomach. "Gastric cancer cells also release Galectin-3-rich exosomes that remodel the peritoneum into a fibrotic, CXCL12-laden niche, thereby favoring trans-coelomic dissemination—the dominant metastatic route of this disease." (PMID 40710343, 2025). "For example, polysaccharides extracted from Spirulina platensis also inhibited the growth of gastric cancer cells via modulation of galectin-3 and exhibited cyto/DNA Protection." (PMID 39446747, 2024). "Our purpose was to assess its influence on apoptosis, Bax, caspases, MUC1, cancer-related carbohydrate antigens, enzymes participating in their formation, and galectin-3 in AGS gastric cancer cells." (PMID 34681197, 2021). "To analyze the in vivo effect of hTERT overexpression and galectin-3-depletion in gastric cancer tumorigenesis, we prepared stable cell lines and xenografted them into nude mice." (PMID 27494887, 2016). "The size of tumor burdens was increased in hTERT-overexpressed gastric cancer cells xenografted mice, whereas it was repressed by concomitant depletion of galectin-3." (PMID 27494887, 2016). "Knockdown of galectin-3 induced-cellular senescence was decreased by overexpression of hTERT in gastric cancer cells." (PMID 27494887, 2016). "We demonstrate that hTERT regulates cellular senescence and that galectin-3 regulates hTERT expression and activation in gastric cancer." (PMID 27494887, 2016). "Consistent with the finding that galectin-3 expression increases in gastric cancers, the expression of galectin-3 was higher in AGS cells as demonstrated by Western blotting and an immunostaining-based flow cytometric analysis." (PMID 26934444, 2016). "In gastric cancers, galectin-3 increases cell motility by upregulating fascin-1, protease-activated receptor-1, and matrix metalloproteinase-1 expression levels." (PMID 26934444, 2016). "Consistent with the results of previous studies showing that galectin-3 is required for gastric cancer cell growth, galectin-3 silencing significantly inhibited the growth of AGS cells." (PMID 26934444, 2016). "Previously, we reported DNA microarray analysis results using galectin-3 depleted AGS gastric cancer cells." (PMID 27494887, 2016). "In order to further explore how galectin-3 increases neogenin-1 expression in gastric cancer cells, we focused on the transcription factor, heat shock factor 1 (HSF-1), as a major regulator of heat shock protein transcription." (PMID 24930499, 2014). "Through previous studies (GSE 29630), we reported microarray data on galectin-3 silencing in gastric cancer cell lines which indicated that several cell motility-related genes changed." (PMID 24930499, 2014). "Taken together, our results suggest that neogenin-1 increases gastric cancer cell motility, and its expression is highly regulated in gastric cancers through interactions with galectin-3 and HSF-1." (PMID 24930499, 2014). "The expression levels of galectin-3 and neogenin-1 were analyzed in 20 gastric cancer patients obtained from the National Cancer Center of Korea." (PMID 24930499, 2014). "Fascin-1 was also involved in Galectin-3, a beta-galactoside-binding protein, mediated gastric cancer cell motility increasement." (PMID 25433493, 2014). "Galectin-3 plays the key role of activating cell surface receptor through production of protease and boosts gastric cancer metastasis." (PMID 21966428, 2011). "Galectin-3 has the potential to serve as a useful pharmacological target for prevention of gastric cancer metastasis." (PMID 21966428, 2011). "To clarify the role of galectin-3 in cancer metastasis, we knocked-down its expression in gastric cancer cells using its siRNA and examined the results in gene expression by DNA microarray analysis." (PMID 21966428, 2011). "In previous studies, we found that galectin-3 increases gastric cancer cell motility by up-regulating fascin-1, an actin-bundling cytoskeletal protein." (PMID 21966428, 2011).
gastric cancer (continued). "In conclusion, our studies demonstrated that galectin-3 accelerated gastric cancer cell motility by up-regulating of PAR-1 and MMP-1." (PMID 21966428, 2011). "In another study, a negative correlation was found between the expression levels of Li-cadherin and Galectin-3 in gastric cancer, while galectin-3 expression was related to TNM staging (Tumor, Nodes, Metastases)." (PMID 23658855, 2010). "In another study, positive galectin-3 expression was observed in 84% of the gastric cancer cases and galectin-3 expression in gastric carcinoma compared with that in gastric tissues adjacent to the cancers demonstrated a significant increase." (PMID 23658855, 2010). "Galectin-3 was detected in normal gastric epithelial cells and in all gastric carcinoma specimens, albeit in varying amounts." (PMID 23658855, 2010). "Additionally, the pool of nuclear galectin-3 is augmented by a proline to histidine substitution at position 64, observed in breast and gastric cancers, thereby promoting cancer progression." (PMID 38990375, 2024). "Consequently, increased expression and co-localization of β-catenin, pSTAT3, and galectin-3 in patients with advanced gastric cancer correlates with a poorer prognosis." (PMID 38990375, 2024). "Kada found that decreased expression of Galectin-3 in gastric cancer indicated poor prognosis." (PMID 33820866, 2021). "Expression of galectin-3 is increased in primary gastric cancer and metastatic lymph nodes." (PMID 26934444, 2016). "Next, we determined whether galectin-3 regulates the function of hTERT on the proliferation of gastric cancer cells." (PMID 27494887, 2016). "Knockdown of galectin-3 decreased the expression of hTERT in gastric cancer cells." (PMID 27494887, 2016). "Therefore, in this study, we determined the interaction between hTERT and galectin-3 to regulate cellular senescence in gastric cancer." (PMID 27494887, 2016). "Knockdown of galectin-3 significantly decreased hTERT expression levels in gastric cancer cells." (PMID 27494887, 2016). "Therefore, we determined mRNA expression levels and correlation between hTERT and galectin-3 in twelve gastric cancer cell lines." (PMID 27494887, 2016). "The galectin-3-increased gastric cancer cell motility was down-regulated by HSF-1 depletion." (PMID 24930499, 2014). "Therefore, our results strongly suggest that neogenin-1 was more detected in malignant tissues and its expression was positively correlated with both HSF-1 and galectin-3 in the malignant tissues of gastric cancer patients." (PMID 24930499, 2014). "Galectin-3 and galectin-4 may be useful tumor markers for gastric cancers with respect to tumor progression and potentiality of lymph node metastasis especially in certain histological types of gastric cancer." (PMID 24339967, 2013). "This study demonstrated that galectin-3 enhanced gastric cancer cell migration and invasion." (PMID 21966428, 2011). "Based on these data galectin-3 and probably galectin-4 might be useful tumor markers for gastric cancers with respect to tumor progression and potentiality of lymph node metastasis especially in certain histological types of gastric cancer." (PMID 23658855, 2010). "For example, although galectin-3 has been proven to be related to poor survival and play an oncogenic role in many types of cancer, such as ovarian, colorectal, and non-small cell lung cancer, high expression of galectin-3 appears to better predict survival in patients with gastric cancer." (PMID 31832021, 2019). "Therefore, this study suggests that hTERT could be potent prognostic and therapeutic targets in gastric cancer therapy; further galectin-3 is an important regulator of hTERT expression and telomeric activity in gastric tumorigenesis." (PMID 27494887, 2016). "The concordance between transcriptomic signatures and protein-level validation by IHC preliminary establishes LGALS3 and LPCAT1 as functionally relevant biomarkers in gastric cancer immunotherapy response." (PMID 40723289, 2025).
gastric cancer (continued). "Binding of galectin-3 to the transcription factor STAT3 enhances its Tyr-705 phosphorylation, leading to its nuclear translocation and transcriptional activation in gastric cancer tissues." (PMID 38990375, 2024). "Using the top eight upregulated genes (SLPI, PLA2G2A, CXCL1, CCL20, REG1A, CLDN7, PI3, LGALS3) as a representative gene set for the high metabolic subcluster, we calculated the GSVA score of this gene set for each patient in the TCGA gastric cancer cohort." (PMID 38831933, 2024). "We finally verified the mRNA expression of EZH2, G6PD, LGALS3 and PSMD14 by qRT-PCR in clinical gastric cancer tissue samples." (PMID 37853322, 2023). "Increased expression levels of Galectin-3 and MMP-1 were also found in gastric cancer cells, with similar effects of Galectin-3 on MMP-1." (PMID 32455781, 2020). "In MKN45 gastric cancer cells, a molecular complex comprised of integrin α6β4, EGFR, and galectin-3 has been reported." (PMID 31052260, 2019). "Because SHP2 can be activated by the PI3K/AKT-mediated pathway, aberrant expression of galectin-3, an oncogenic protein that acts upstream of AKT, was next examined in gastric cancer cells." (PMID 26934444, 2016). "In the present study, we investigated the crosstalk of galectin-3 with AKT/GSK-3β signaling and IFN-γ resistance in gastric cancer cells." (PMID 26934444, 2016). "This study investigated the potential role of galectin-3, which acts upstream of AKT/GSK-3β/SHP2, in gastric cancer cells." (PMID 26934444, 2016). "We also reported that galectin-3 interacts with GSK-3b and then regulates WNT signaling to promote gastric cancer motility." (PMID 27626163, 2016). "Taken together, our results demonstrated that HSF-1 increases gastric cancer cell motility through regulation of neogenin-1 expression, and the transcriptional activation of HSF-1 is regulated by galectin-3." (PMID 24930499, 2014). "Taken together, high-expression of neogenin-1 promotes gastric cancer proliferation and motility and its expression is regulated by HSF-1 and galectin-3 interaction." (PMID 24930499, 2014). "We also determined the expression levels of galectin-3, PAR-1 and MMP-1 in malignant tissues from gastric cancer patients for clinical correlations between these proteins in human specimens." (PMID 21966428, 2011). "This possibility is supported by our finding of parallel and co-localized expressions of galectin-3 and PAR-1 in malignant tissues of gastric cancer patients." (PMID 21966428, 2011). "f) Galectin-3, PAR-1, and MMP-1 are highly expressed and co-localized in malignant tissues from gastric cancer patients." (PMID 21966428, 2011). "We examined the expression levels of Galectin-3, PAR-1, and MMP-1 in gastric cancer patient tissues and also the effects of silencing these proteins with specific siRNAs and of over-expressing them using specific lenti-viral constructs." (PMID 21966428, 2011). "We confirmed that up-regulation of MMP-1 by galectin-3 is important for the activation of PAR-1 signaling and increased gastric cancer cells invasion." (PMID 21966428, 2011). "We determined the mRNA and protein expression levels of galectin-3, PAR-1 and MMP-1 in normal and malignant tissues from 20 gastric cancer patients, then employed RT-PCR using an image J analyzer." (PMID 21966428, 2011). "This study reveals distinct molecular profiles in gastric cancer immunotherapy responders (IL1B/IFN-γ-driven immunity) versus non-responders (galectin-3/complement-mediated suppression)." (PMID 40723289, 2025). "Another example of galectin-3 as a transcription effector is provided by interaction with the HSF-1 transcription factor to promote expression of the cell adhesion molecule neogenin-1, cell survival in gastric cancer and cell motility." (PMID 38990375, 2024). "Previously, we reported that galectin-3 regulates cellular senescence without oncogenic stress in gastric cancer." (PMID 27494887, 2016).
gastric cancer (continued). "Therefore, we demonstrate herein the effects of neogenin-1 on gastric cancer cell proliferation and migration, as well as the regulation of its expression by HSF-1 and galectin-3 interactions." (PMID 24930499, 2014). "Moreover, parallel and high expression of neogenin-1 and galectin-3, as well as neogenin-1 and HSF-1, was detected in human gastric cancer tissue." (PMID 24930499, 2014). "Moreover, the parallel expression patterns of galectin-3 and neogenin-1, as well as those of HSF-1 and neogenin-1, were detected in the malignant tissues of gastric cancer patients." (PMID 24930499, 2014). "Interestingly, galectin-3 interacted with HSF-1 directly, which facilitated nuclear-localization and binding on neogenin-1 promoter to drive its transcription and gastric cancer cell motility." (PMID 24930499, 2014). "hese findings led us to hypothesize that galectin-3, PAR-1 and MMP-1 may be involved in enhancing the migration and invasion of gastric cancer." (PMID 21966428, 2011). "The expression levels of galectin-3 and PAR-1 were high in most gastric cancer cell lines." (PMID 21966428, 2011). "Therefore, an increase in MMP-1 expression promoted by galectin-3 might have dual effects, namely, PAR-1 activation and ECM degradation, and both are critical for gastric cancer metastasis." (PMID 21966428, 2011). "This study showed that RFP labeled gastric cancer cells invaded blood vessels while galectin-3, MMP-1 or PAR-1 silenced gastric cancer cells could not." (PMID 21966428, 2011). "Through the DNA microarray studies after galectin-3 silencing, we demonstrated here that galectin-3 plays a key role in up-regulating the expressions of protease-activated receptor-1(PAR-1) and matrix metalloproteinase-1(MMP-1) PAR-1 thereby promoting gastric cancer metastasis." (PMID 21966428, 2011). "However, to our knowledge, no other reports related to galectin 3, S100A10, desmoplakin, occludin, keratins 8, 14, myosin VI, tubulin beta 4 and calveolin-3 in gastric cancer have been published." (PMID 12402156, 2002).
viral infection (45 papers, 2006 to 2026). "Many studies have revealed that galectin-3 plays an important role as a diagnostic or prognostic biomarker for certain types of heart disease, kidney disease, viral infection, autoimmune disease, neurodegenerative disorders, and tumor formation." (PMID 32138174, 2020). "We observed that galectin-3 expression may be a pivotal mediator of cardiac fibrotic degeneration in early phase of myocarditis following EMCV infection, and that detection of serum galectin-3 might be an early diagnostic biomarker for cardiac degeneration in acute myocarditis after virus infection." (PMID 30673749, 2019). "Thus, our results show that detection of galectin-3 might be an early diagnostic method for myocardial degeneration after virus infection." (PMID 30673749, 2019). "Galectin-3 (Gal3), a member of the β-galactoside-binding protein family, has been shown to play a pivotal role in host–pathogen interactions and viral infections." (PMID 39125989, 2024). "Galectin-3 can sometimes have a protective role during viral infections, promoting antiviral immunity and limiting viral spread, which contributes to host protection and recovery." (PMID 37298569, 2023). "Concerning the role of galectin-3 in viral infections, it can participate in interactions taking place between virus and host during viral entry, viral replication, or immune response modulation." (PMID 37958814, 2023). "Galectin-3 is a multifaceted protein that plays a crucial role in various aspects of viral infections, with diverse and sometimes contrasting effects depending on the virus and the host’s immune response." (PMID 37298569, 2023). "Galectin-3, a multifunctional protein with roles in various biological processes, has emerged as an important player in the context of viral infections." (PMID 37298569, 2023). "Galectin-3 is expressed abundantly during viral infections in various immune cells, fibroblasts, and epithelial and endothelial cells." (PMID 37298569, 2023). "Host–Virus Interactions: Galectin-3’s role in modulating the host immune response to viral infections needs further exploration." (PMID 37298569, 2023). "Galectin-3 influences immune cell activation and recruitment during viral infection, modulating the activation of T cells, dendritic cells, macrophages, and neutrophils and affecting their cytokine production and chemotactic responses." (PMID 37298569, 2023). "Most relevant for this review, galectin-3 also influences inflammatory processes and viral infection." (PMID 37238973, 2023). "Extracellular galectin-3 can act as the glycan bridge between the host and pathogens or binding partners for viral infection." (PMID 36823664, 2023). "Galectin-3 has also been identified as a herpes simplex virus type 1 entry mediator in corneal keratinocytes, thus facilitating viral infection." (PMID 36823664, 2023). "Galectin-3 plays a pivotal role in modulating immune signaling pathways during viral infections, either activating or inhibiting these pathways depending on the cellular context, which influences the immune response." (PMID 37298569, 2023). "In the BAL fluid, the amount of galectin-3 of 30 kDa was upregulated following viral infection, as examined by ELISA and immunoblotting." (PMID 36823664, 2023). "We demonstrate that galectin-3 enhances viral infection through increases in vRNP nuclear import and RdRp activity, thereby facilitating viral transcription and replication." (PMID 36823664, 2023). "Through addressing these areas, future research can provide a more complete picture of how Galectin-3 influences viral infections and inform the development of novel therapeutic strategies." (PMID 37298569, 2023). "Other studies involving human viral infections such as the herpes simplex virus and the varicella-zoster virus suggest a role for galectin-3, with a specific focus on the regulation of adaptive immunity." (PMID 37958814, 2023).